CCND1 (cyclin D1)
Diseases named in the same sentence as CCND1 in open-access papers (continued):
Sharing a sentence is not in itself a finding about the gene and the disease.
lung carcinoma (continued). "Interestingly, in vitro results exhibited marked diminutions in NF-κB, Cyclin D1, p-AKT, and VEGF1 after treatment with sericin + dactolisib and sericin + vitamin D compared to control lung cancer cells and those treated with a single drug." (PMID 39505930, 2024). "In lung cancer, SETD7 can inhibit cell proliferation by downregulating cyclins (CCNA1 and CCND1)." (PMID 39522095, 2024). "Importantly, PRMT5‐mediated KLF5 stabilisation induced the expression of target genes such as cyclin D1, slug and FGF‐BP1, which facilitated lung cancer cell proliferation and EMT." (PMID 37461162, 2023). "Furthermore, a recent investigation showed a reduction in c-Myc, Cyclin D1 and CDK6 in si-USP28-treated lung cancer cell lines." (PMID 36879346, 2023). "In order to examine whether the nuclear translocation of NF-κB has an effect on CCND1 expression, we used the NF-κB inhibitor SN50, which can effectively inhibit the nuclear translocation of NF-κB, to treat lung cancer cells." (PMID 35246017, 2022). "Rk3 could downregulate the expression of cyclin D1 and CDK4, upregulate the expression of P21 protein, and inhibit the proliferation and colony formation of lung cancer cells." (PMID 36569343, 2022). "In addition, survival analyses indicate a higher survival probability for low CCND1 and high AATK expression in HNSCC, pancreatic ductal adenocarcinoma (PDA) and lung cancer (lung squamous cell carcinoma and adenocarcinoma)." (PMID 35902728, 2022). "Moreover, it has been reported before our study that both Cyclin D1 and CDK6 worked as downstream of Akt signaling pathway in the regulation of lung cancer and colorectal cancer." (PMID 33902600, 2021). "Exposure of HCT116 and SW480 colorectal cancer cells to patchouli alcohol activated p21 expression and inhibited the expression of cyclin D1 and CDK4 and induced cell apoptosis and cell cycle arrest in A549 lung cancer cells in vitro and in vivo via the EGFR-MAPK pathway." (PMID 32963578, 2020). "However, three hub genes JUN, FGF2, CCND1 and IL6 expressed fewer mRNAs in lung cancer tissues than normal lung tissues." (PMID 32210363, 2020). "In lung cancer, it has been demonstrated that increased levels of nuclear phosphorylated FADD induce NF-κB, which is suggested to induce the expression of cyclin D1 (CCND1) at the transcriptional level, ultimately resulting in cell cycle deregulation." (PMID 31569512, 2019). "Next, we evaluated whether the CTNNBIP1 expression was related to changes in the expression of various β-catenin-targeted genes, such as MMP7, cyclin D1, and c-MYC, among these lung cancer patients." (PMID 31766223, 2019). "In addition, western blotting analysis of lysate from lung cancer cells treated with STX-0119 showed that STX-0119 decreased the expression of STAT3 target proteins such as c-Myc, cyclin D1, and survivin in a concentration-dependent manner." (PMID 32257917, 2019). "It was found that ZNF322A, previously identified as an oncoprotein, could promote tumor cell growth and metastasis in lung cancer via ADD1 and CCND1; knockdown of ADD1 would suppress lung cancer cell migration and invasion." (PMID 29862265, 2018). "Cyclin D1 is the main regulator of CDK4/6 and is upregulated in most lung cancer cells." (PMID 29764507, 2018). "Some genes such as MMP11 (extra-cellular matrix proteins), XRCC1 (DNA repair), VEGF (regulator of angiogenesis), Cyclin D1 (cell cycle regulators) and tumor-suppressor genes (Semaphorin 3B, WNT-5A) have been found as down-regulated genes during lung cancer progression." (PMID 29593668, 2018). "In deed, the expression of cyclin D1, cyclin E2, and cyclin D3 were downregulated in CHRNA5 shRNA transfected lung cancer cells, suggesting that the G0/G1 phase to S phase transition might be regulated by α5-nAChR through cell cyclins." (PMID 28878681, 2017).
lung carcinoma (continued). "cyclin D1 is important oncogene that shown strong power of oncogenicity, by promotion of cell growth, migration, invasion and epithelial mesenchymal transition (EMT), as well as inhibition of cell apoptosis in many tumors including lung cancer." (PMID 26840018, 2016). "Similarly, the mRNA expression levels of CCND1 and CDC2, both of which are known AP-1 target genes, were significantly decreased in TOPK knockdown compared to the parental lung cancer cells." (PMID 26745678, 2016). "In addition, E2F8 was reported to transcriptionally upregulate cyclin D1 in hepatocellular carcinoma, and UHRF1 in lung cancer." (PMID 26992224, 2016). "TBBX induced G1 cell cycle arrest might be through down-regulation HDAC6 expression and followed by hyper-acetylation of Hsp90 and accelerating cyclin D1 and CDK4 degradation in H1299 lung cancer cells." (PMID 25946558, 2015). "In addition, miR-206 also inhibited CCND1 and CCND2 and increased p57 expression levels in lung cancer cells, which further contributed to the growth-delay efficacy of miR-206." (PMID 26325180, 2015). "Furthermore, our study revealed that MAP3K3 regulates the cell cycle through effects on CDC25A, CCND1/2 and CCNE1 regulation in lung cancer." (PMID 26088427, 2015). "Second, miR-206 can directly regulate mRNA expression by targeting the 3′-UTR of MET and BCL2, and inhibit protein expression of cyclin D1 and gene expression of cyclin D1, cyclin D2 and matrix metalloproteinase 9 (MMP-9), while increased p57 gene expression in lung cancer cell (A549)." (PMID 26325180, 2015). "To further confirm the reciprocal relationship between HBP1 expression and β-catenin activity in lung cancer, we examined whether HBP1 knockdown would affect β-catenin/TCF activity and increase c-MYC and cyclin D1 expression." (PMID 24895061, 2014). "Our results indicate that overexpression of cyclin D1 and CDK4 in lung cancer tissues may partially result from the underexpression of miR-545." (PMID 24505359, 2014). "In conjunction with the data obtained from lung cancer cell lines, it is highly likely that ATDC may upregulate cyclin D1 and c-Myc and in turn accelerate cell cycle progression in NSCLC." (PMID 23776433, 2013). "The results of our study and meta-analysis consistently suggest that the predictive role of CCND1 rs9344 in therapeutic efficacy and prognosis of lung cancer patients may not be effective for all individuals, but rather requires more precise subgroup analysis." (PMID 38589850, 2024). "Additionally, the deregulation of Let-7 miRNA has been demonstrated to be a feature of numerous cancers specifically lung cancer, Let-7a miRNA may target a number of genes, including RAS, Myc, Hmga2, and Cyclin D1." (PMID 37845669, 2023). "Western blot showed that knockdown of MTFR2 inhibited the activation of the AKT pathway and SC79 can partially reduce si-MTFR2-induced decreased p-AKT and Cyclin D1 expression, suggesting that MTFR2 could regulate lung cancer proliferation through the AKT signaling pathway." (PMID 35600359, 2022). "Thus, we next examined cyclin D1 expression in NSCLC and pair-matched adjacent lung tissues, and our western blot results demonstrated that cyclin D1 protein level was increased in lung cancer tissues in comparison to normal lung tissues (3.4-fold of increase)." (PMID 27166267, 2016). "However, inhibition of miR-326 does not reverse the anticancer efficacy of silence of CCND1 expression in lung cancer cell lines (both A549 and SPC-A-1 cells)." (PMID 26840018, 2016).
lung carcinoma (continued). "Since c-Met is the target protein of an important proto-oncogene MET, Bcl2 plays anti-apoptosis role in vivo and vitro, and cyclin D1 is the key role on regulation of cell cycle regulated by MET, aberrations of these three proteins might contribute to human lung cancer." (PMID 26325180, 2015). "c-Met, Bcl2 and cyclin D1 are important oncogene that shown strong power of oncogenicity, by promotion of cell growth, migration, invasion and epithelial mesenchymal transition (EMT), as well as inhibition of cell apoptosis in many tumors including lung cancer." (PMID 26325180, 2015). "Cyclins are often upregulated in cancers; however, cyclin D1 has not been shown to be a negative prognostic factor in cancer, cyclin D2 is often methylated and thus downregulated in lung cancer, and cyclin D3 was suggested not to have a profound role in tumorigenesis." (PMID 25325012, 2014). "Interestingly,dysregulation of cyclin D1 was found in 11 out of 16 (69%)chromium-induced lung SCC but only 3 out of 26 (12%) non-exposed lungSCC, indicating a specific connection between cyclin D1overexpression and the lung cancer induced by chromate exposure." (PMID 21437242, 2011). "Furthermore, 'classic' oncogenes such as cyclin D1 are found by the PPST test in the lung cancer data set are not reported to be significant by the t-test." (PMID 15307894, 2004). "However, whether there is a direct binding relationship between NF-κB and CCND1 in lung cancer has not been reported." (PMID 35246017, 2022). "Importantly, ARAP1-AS1 was previously demonstrated to be highly expressed in lung cancer tissues and cells, and ARAP1-AS1 knockdown markedly inhibited the proliferation of lung cancer cells and induced cell cycle arrest by decreasing the expression of cell cycle-related protein cyclin D1." (PMID 35291911, 2022). "Besides, NT157 decreased expression of oncogenes BCL2, CCND1, MYB, and MYC and increased genes related to cellular stress and apoptosis, JUN, BBC3, CDKN1A, CDKN1B, FOS, and EGR1 (p < 0.05), favoring a tumor-suppressive cell signaling network in the context of lung cancer." (PMID 36224313, 2022). "However, cyclin D1 expression was not affected by metformin in lung cancer cells while E2F1 knockout cells showed normal proliferation in a mouse model, implying that other factors may be involved in metformin-induced cell cycle arrest in lung cancer cells." (PMID 29254182, 2017). "The overexpression of BTG2 may inhibit the growth and proliferation through inhibiting the protein expression of cyclin D1, and invasiveness through inhibiting the protein expression of MMP-1 (matrix metalloproteinase-1) and MMP-2 (matrix metalloproteinase-2) in the A549 human lung cancer cell line." (PMID 26132560, 2015).
colon carcinoma (372 papers, 2004 to 2026). "Wnt signaling is aberrantly activated in approximately 80% of colon cancers, and its downstream genes, including cyclin D1, cyclin E1, and c-Myc, are implicated in the proliferation and metastasis of colon cancer cells." (PMID 40104500, 2025). "According to the mechanistic studies, formononetin is able to inhibit the growth of colon cancer cells by downregulating the expression of the cell cycle-associated protein (cyclin D1) and causing cell cycle arrest at the G0/G1 checkpoint." (PMID 37298670, 2023). "Consistently, lower expression of β-catenin target genes was observed in TGR5-deficient colon tumor organoids, including Myc and Ccnd1." (PMID 36765047, 2023). "Quercetin inhibits growth of human SW480 colon cancer cells in association with inhibition of cyclin D1 and surviving expression through Wnt/beta-catenin signaling pathway." (PMID 32575531, 2020). "CDK2 was identified as a direct target of curcumin in colon cancer cells, and germacrone induces G1 phase arrest, associated with a significant decrease in expression of cyclin D1 and CDK2 and elevated expression of p21." (PMID 29636777, 2018). "Previous reports found that miR-374a reduced mortality in CRC cases and high levels of CCND1 were associated with poor prognosis in colon cancer." (PMID 27191497, 2016). "Nevertheless, single cell and MELF pattern in endometrial carcinoma, budding in colon cancer and pT3 tumors of prostatic carcinomas each of them exhibiting membranous-cytoplasmic Ccnd1 expression, have been associated with aggressiveness." (PMID 27105504, 2016). "The transcription of cyclin D1 is activated by the accumulation of β-catenin as a result of loss of functional adenomatous polyposis coli protein in colon cancer." (PMID 26121043, 2015). "Colon cancer has been also shown to be associated with an overexpression of growth promoting cell cycle regulators such as cyclin D1." (PMID 26839513, 2015). "In light of these observations, we investigated the association of T-Antigen and nuclear β-catenin in colon cancer cases and the effects of this complex in the activation of the transcription and cell cycle regulators c-Myc and Cyclin D1 in vitro." (PMID 25229241, 2014). "Cyclin D1 expression in colon tumours is probably linked to its cell cycle-promoting activity in this tissue since expression of cyclin D1 antisense inhibited growth and tumorigenicity of human colon cancer cells." (PMID 16012517, 2005). "We analyzed the relationship between mRNA expression and OS in this network, and we found that high expression of CCND1 and VEGFA is an indicator of poor prognosis for colon cancer and that the expression of CCND1 and VEGFA is associated with macrophage infiltration." (PMID 34922547, 2021). "Our data also suggest that chronic exposure to an n-6HFD downregulates APC expression via CpG hypermethylation and this associates with increased expression of COX-2 via PTSG-2 CpG hypomethylation and accumulation of C-JUN and CCND1, thus increasing the risk of inflammation and cancer of the colon." (PMID 30650553, 2019). "Consistently, the protein levels of STAT3 downstream target genes Bcl-xl, c-Myc, Pcna, and Ccnd1, which were responsible for tumor cell survival and proliferation, respectively, were dramatically downregulated in colon tumors of TRIM27-deficient mice compared to their wild-type littermates." (PMID 30143645, 2018). "Thus, our findings confirm that, regardless of the nature of cell lines, induction of antiproliferation by promoting cyclin D1 proteasomal degradation is a universal mechanism or action underlying obatoclax-mediated anti-colon cancer activity." (PMID 28035994, 2016).
colon carcinoma (continued). "However, epigenetic activation of Ptsg-2 coupled with silencing of Apc and accumulation of C-JUN and Ccnd1 may increase the risk of inflammation and cancer of the colon." (PMID 30650553, 2019). "Trametinib reduces the expression of cyclin D1 in canine melanoma cells, as well as cell lines of human non-small cell lung cancer, melanoma, and colon cancer." (PMID 40568110, 2025). "Expression levels of Pcna, Ccnd1(CyclinD1), Bcl2, Itga2, Itgb1, Fak, Pik3r1, Akt1, Mtor and Myc were remarkably upregulated and Bax was downregulated in colonic tumors of mice treated with S. moorei." (PMID 39990665, 2025). "miR-136 offers a novel pathway for the inhibition of Wnt signaling by significantly reducing the expression of cyclin D1, cyclin E1, and c-Myc in colon cancer through LRH-1 suppression." (PMID 40104500, 2025). "The treatment of colon cancer cells with various concentrations of TAGP led to the repression of Cyclin D1 and c-Myc level." (PMID 40730487, 2025). "Trametinib reduces the expression of cyclin D1 in canine MM cells, as well as cell lines of human non-small-cell lung cancer, melanoma, and colon cancer." (PMID 40723239, 2025). "Sohlh2 suppressed the proliferation, migration, and invasion of ovarian, breast and colon cancer cells through transcriptional regulation of P21, Cyclin D1 and APC." (PMID 40418209, 2025). "Quinoa saponin induced significant G0/G1 phase arrest in HT‐29 cells by regulating the expression of Cyclin D1 and P21, thereby inhibiting the proliferation of colon cancer cells." (PMID 39803233, 2025). "Herein, we focused on colon cancer to figure out the remedial impacts related to the secretome of MSCs (as a new strategy) through EGFR/c-Src/IRSp53/p-AKT/p-Stat3/cyclin D1 signaling pathway." (PMID 41200137, 2025). "Therapeutic doses of the betanin/capecitabine combination significantly downregulated the mRNA expression of the parameters TNF-α, NFκB, IL-1β, IL-6, and cyclin D1 compared to the colon cancer control." (PMID 38645563, 2024). "lactis and its cell wall have antiproliferative and antitumor effects by decreasing cyclin D1 in SW480 colon cancer cell lines." (PMID 39600571, 2024). "Inhibition of eukaryotic translation elongation factor 1 alpha 1 by Nannocystin Ax has been reported to inhibit translation of new proteins and downregulate cyclin D1, inducing G1 cell cycle arrest in colon cancer cells." (PMID 38968330, 2024). "In the present study, our aim was to test the chemopreventive activity of the betanin/capecitabine combination in a model of chemically induced colon cancer and explore the possible inhibition of NFκB signaling and cyclin D1 protein using bioinformatic tools." (PMID 38645563, 2024). "Contrary to the upregulation observed in PDCOs, incubation of colon cancer cells with MDEs resulted in the downregulation of both β-catenin and cyclin D1." (PMID 39769282, 2024). "IGF2BP3 has been reported to be highly expressed in colon cancer and promote cancer cell proliferation by reading m6A modification of CCND1." (PMID 38353724, 2024). "A colon cancer-based study reported that formononetin inhibited cell proliferation and invasion via the inhibition of cyclin D1 and MMP-2/9 expression through p-STAT3, p-PI3K, and p-Akt inactivation." (PMID 37298670, 2023). "In this respect, it is worth noting that GPR15L has been recently reported to interact with SUSD2 to inhibit colon cancer cell growth via G1 arrest, which is induced by down-regulating cyclin D1 and cyclin-dependent kinase 6 (CDK6)." (PMID 38074634, 2023).